DGKK (diacylglycerol kinase kappa)
Description:
Diacylglycerol kinase that converts diacylglycerol/DAG into phosphatidic acid/phosphatidate/PA and regulates the respective levels of these two bioactive lipids. Thereby, acts as a central switch between the signaling pathways activated by these second messengers with different cellular targets and opposite effects in numerous biological processes (Probable).
Tractability: Antibody: UniProt places it where antibodies can reach, with high confidence; its Gene Ontology location is reachable by antibodies, with high confidence.
Target class: Enzyme; Transferase
Gene: Protein-coding gene on chromosome X (50,365,405 to 50,470,850, reverse strand). Ensembl gene ENSG00000274588.
Subcellular location: Cell membrane
Pathways (Reactome):
Hemostasis: Effects of PIP2 hydrolysis
Gene Ontology:
Molecular function: ATP-dependent diacylglycerol kinase activity; protein binding; kinase activity
Biological process: diacylglycerol metabolic process; intracellular signal transduction; response to oxidative stress; phosphatidic acid biosynthetic process; platelet activation; glycerolipid metabolic process; phospholipase C-activating G protein-coupled receptor signaling pathway; signal transduction
Cellular component: plasma membrane
Homologues: Orthologues: chimpanzee DGKK (99% identical), macaque DGKK (96% identical), pig DGKK (85% identical), dog DGKK (82% identical), rabbit DGKK (79% identical), rat Dgkk (77% identical), mouse Dgkk (76% identical), guinea pig DGKK (68% identical), Drosophila melanogaster CG34384 (32% identical), Caenorhabditis elegans dgk-4 (28% identical), Drosophila melanogaster Dgk (16% identical), Drosophila melanogaster rdgA (15% identical), and 4 more. Paralogues in human: DGKH (36% identical), DGKD (36% identical), DGKB (16% identical), DGKG (16% identical), DGKQ (16% identical), DGKA (16% identical), DGKI (16% identical), DGKZ (15% identical), DGKE (15% identical).
Diseases named in the same sentence as DGKK in open-access papers:
DGKK is named in the same sentence as 11 diseases in open-access papers, as found by Europe PMC text mining. Sharing a sentence is not in itself a finding about the gene and the disease. The quoted sentences say what the papers report.
hypospadias (14 papers, 2015 to 2026). Hypospadias is the displacement of the urethral meatus on the ventrum of the penis. "GWAS studies implicate several of these developmental regulators to be correlated with hypospadias risk, with risk loci near DGKK, and multiple developmental genes." (PMID 41596366, 2026). "DGKK was associated with hypospadias in humans and Holstein cattle, which is a congenital defect of the genital region." (PMID 39682483, 2024). "DGK kappa (DGKK) participates in fragile X syndrome, and its nucleotide variants are associated with hypospadias." (PMID 36959535, 2023). "One variant, a base change, on the X-chromosome was detected in the candidate gene DGKK, which is reported as a major risk gene for mild to moderate hypospadias phenotypes in humans." (PMID 31923267, 2020). "For example, DGKθ and DGKκ have been suggested to be associated with susceptibility to Parkinson's disease and hypospadias, respectively." (PMID 27583247, 2016). "Genetic variants in DGKK have been strongly associated with risk for hypospadias." (PMID 36397165, 2022). "A genome-wide association study indicated that DGKκ is involved in hypospadias." (PMID 25613821, 2015). "A genome-wide association study also indicated a potential relationship between DGKκ and hypospadias, a common congenital malformation of the male external genitalia." (PMID 36982774, 2023). "The authors also found SNPs in DGKκ in additional Dutch and Swedish cohorts of anterior or middle hypospadias cases." (PMID 27583247, 2016). "A genome-wide association study also indicated a potential relationship between DGKκ and hypospadias." (PMID 25613821, 2015). "Several genes have been founded to link with hypospadias such as DGKK, ESRs, HOX, ATF3 and VAMP." (PMID 39959693, 2025). "Carmichael and colleagues found an increased risk association for several diacylglycerol kinase kappa (DGKK) gene SNPs for mild to moderate hypospadias but not for severe hypospadias." (PMID 32391298, 2020). "Variants in Diacylglycerol Kinase Kappa (Dgkk) have been described in association with hypospadias, but no functions in the heart have been reported." (PMID 30241514, 2018). "In addition, significant associations of DGKK SNPs variants were found by Xie and colleagues for mild and moderate hypospadias when compared to controls, but not for severe hypospadias when compared to controls." (PMID 32391298, 2020).
fragile X syndrome (3 papers, 2020 to 2023). A genetic syndrome caused by mutations in the FMR1 gene which is responsible for the expression of the fragile X mental retardation 1 protein. "DGK deficiency is directly or indirectly involved in human diseases, such as cancer, atypical hemolytic uremic syndrome, hypospadias (DGKκ), diabetes, and mood and cognitive disorders, including Parkinson’s disease and fragile X syndrome, a primary cause of autism and inherited cognitive disorder." (PMID 32962151, 2020). "Brain neuron‐restricted expression of an FMRP‐independent DGKk enzyme via intra‐cerebral adeno‐associated virus (AAV) gene therapy corrects phosphatidic acid deficiency and rescues disease relevant behavioral phenotypic alterations in a mouse model of Fragile X syndrome (FXS)." (PMID 35373916, 2022). "In fragile X syndrome, a condition in which FMRP-dependent DGKκ translation does not occur, DAG generated from the activation of metabotropic glutamate receptor mGluRI, a GPCR, is not transformed into PA in neurons." (PMID 32962151, 2020).
Sepsis (2 papers, 2023 to 2024). Sepsis is defined as life-threatening organ dysfunction caused by a dysregulated host response to infection. "Increased DGKκ expression in serum extracellular vesicles from patients with sepsis-induced lung injury correlates with sepsis severity and progression." (PMID 39684917, 2024). "EVs derived from lipopolysaccharide (LPS)-treated CD4+ T cells carrying DGKK induced oxidative stress and inflammation in alveolar epithelial A549 cells and sepsis-induced mice through PKC and NOX4, the downstream effectors of DGKK and DAG." (PMID 36959535, 2023). "Elevated level of DGKK in serum EVs from patients with sepsis-induced lung injury was confirmed by ELISA." (PMID 36959535, 2023). "This approach established the mechanism that T-cell-derived EVs carrying DGKK triggered alveolar epithelial cell apoptosis, oxidative stress, inflammation, and tissue damage in sepsis-induced lung injury through the DAG/PKC/NOX4 pathway." (PMID 36959535, 2023). "Our findings demonstrate that the upregulated levels of DGKK in serum EVs derived from septic patients showed strong correlation with sepsis severity and progression." (PMID 36959535, 2023). "This approach established the mechanism that T-cell-derived EVs exerted toxic effects in sepsis-induced lung injury through the DGKK/DAG/PKC/NOX4 pathway." (PMID 36959535, 2023). "Thus, T-cell-derived EVs and the elevated distribution of DGKK should be further investigated to develop therapeutic strategies for sepsis-induced lung injury." (PMID 36959535, 2023). "Encouraged by the findings of elevated distribution of CD4+ T-cell-expressed DGKK in serum EVs from patients with sepsis-induced lung injury, the downstream pathway of DGK was examined for the involvement in the toxic effects of LPS-treated CD4+ T-cell-derived EVs on cultured A549 cells." (PMID 36959535, 2023). "Therefore, this approach established the mechanism that T-cell-derived EVs exerted toxic effects in sepsis-induced lung injury through the DGKK/DAG/PKC/NOX4 pathway." (PMID 36959535, 2023). "Thus, serum exosomal DGKK facilitates tissue damage in the progression of sepsis-induced lung injury." (PMID 36959535, 2023). "In the cultured alveolar epithelial A549 cell line and the lungs of a mouse model of CLP-induced sepsis, EVs derived from CD4+ T cells exerted toxic effects through DGKK and its stimulation on the DAG/PKC/NOX4 signaling pathways." (PMID 36959535, 2023). "The serum diacylglycerol kinase kappa (DGKK) and endotoxin contents of patients with sepsis-induced lung injury were measured." (PMID 36959535, 2023). "DGKK, the key regulator of the DAG/PKC pathway, exhibited elevated expression in serum EVs of patients and showed strong correlation with sepsis severity and progression." (PMID 36959535, 2023). "Mechanistically, EVs derived from LPS-treated CD4+ T cells carrying DGKK induced oxidative stress and inflammation in alveolar epithelial A549 cells and sepsis-induced mice through PKC and NOX4, the downstream effectors of DGKK and DAG." (PMID 36959535, 2023). "DGKK, the key regulator of the diacylglycerol (DAG)/protein kinase C (PKC) pathway, exhibited elevated expression in serum EVs of patients with sepsis-induced lung injury and showed strong correlation with sepsis severity and disease progression." (PMID 36959535, 2023).
Cirrhosis (1 paper, 2022). A chronic disorder of the liver in which liver tissue becomes scarred and is partially replaced by regenerative nodules and fibrotic tissue resulting in loss of liver function. "It is noted that DGKK was significantly correlated with overall survival time of NAFLD patients, which indicated that DGKK could be regarded as a potential prognostic marker molecule for NAFLD of HCC with cirrhosis patients." (PMID 36397165, 2022). "Compared to non-NAFLD of HCC patients with cirrhosis, GNG4, EPCAM, SPARCL1, DGKK, and SLC39A4 were down-regulated and HOXD9 was up-regulated in NAFLD of HCC patients with cirrhosis." (PMID 36397165, 2022).
hepatoma (1 paper, 2019). "DGKK was strongly expressed in the cytoplasm of cancer cells and co-expressed in the nucleus and cytoplasm of few hepatoma cells in high-dose ascorbate samples (4.0 g/kg/3 days IP)." (PMID 31754384, 2019). "Weak cytoplasmic and nuclear staining of DGKK in hepatoma cells and in the low-dose ascorbate samples (2.0 g/kg/3d IP) is shown by the red arrows, whereas the yellow arrows represent the area of ​​necrosis." (PMID 31754384, 2019).
hypothyroidism (1 paper, 2025). Abnormally low levels of thyroid hormone. "Increased P. vulgatus and B. fragilis, decreased DGKK and S10A8 proteins, and a left shift in the Th1/Th2 balance in patients with hypothyroidism in the first half of pregnancy may be associated with the development of the disease." (PMID 40443669, 2025). "Our findings suggest that increased P. vulgatus and B. fragilis, decreased DGKK and S10A8 proteins, and a left shift in the Th1/Th2 balance in patients with hypothyroidism in the first half of pregnancy may be associated with the development of the disease." (PMID 40443669, 2025). "ELISA validation showed that DGKK and S10A8 were significantly down-regulated in patients with hypothyroidism in the first half of pregnancy." (PMID 40443669, 2025). "The proteomic results of this study showed that DGKK and S10A8 were significantly down-regulated in patients with hypothyroidism in the first half of pregnancy." (PMID 40443669, 2025).
melanoma (1 paper, 2023). A malignant, usually aggressive tumor composed of atypical, neoplastic melanocytes. "Notably, it has been suggested that this isozyme changes the balance of signalling lipids in the plasma membrane in response to oxidative stress; this function might explain the increased DGKκ expression induced by CINN-EO as a consequence of the augmented ROS in melanoma cells." (PMID 36982774, 2023). "Intriguingly, the DGKκ isoform has never been found in tumour tissues, while we found it to be expressed in CINN-EO-treated melanoma cells and in melanoma tissue from patients in gene repositories, albeit at low levels (TCGA)." (PMID 36982774, 2023).
tumour (3 papers, 2019 to 2023). "In addition, up-regulated DGKK proteins are detected in HCC tumor tissue samples from mice treated with high-dose ascorbate." (PMID 36397165, 2022). "We validated the gene expression levels of AGER, DGKK, ASB2, TCP10L2, Lnc-ALCAM-3, and Lnc-TGFBR2-1 in HCC tumour tissue samples from mice treated with high-dose ascorbate by qPCR." (PMID 31754384, 2019).
cancer (1 paper, 2019). A tumor composed of atypical neoplastic, often pleomorphic cells that invade other tissues. "Taken together, stronger staining with both anti- AGER/RAGE and -DGKK antibodies was observed in HCC cancer cells treated with high-dose ascorbate (4.0 g/kg/3 days IP)." (PMID 31754384, 2019).
DGKK also shares sentences with these, for which no sentence is quoted: infection (1 paper); Parkinson disease (1).